SMURF2 (SMAD specific E3 ubiquitin protein ligase 2)
Diseases named in the same sentence as SMURF2 in open-access papers (continued):
Sharing a sentence is not in itself a finding about the gene and the disease.
cancer (70 papers, 2003 to 2026). A tumor composed of atypical neoplastic, often pleomorphic cells that invade other tissues. "Smurf2 has been identified as a tumor suppressor gene and is associated with prognosis in a variety of human cancers." (PMID 40978141, 2025). "Elevated SMURF2 expression levels have been observed in connection with various forms of cancer and have been linked to unfavorable prognosis." (PMID 38698292, 2025). "This pathway operates independently of Glutathione Peroxidase 4 (GPX4), another primary regulator of ferroptosis, suggesting an alternative method through which SMURF2 can enhance ferroptotic susceptibility in cancer cells." (PMID 39697237, 2024). "SMURF2 and HIF1α are pivotal regulators in cancer biology, influencing pathways associated with protein degradation, hypoxic response, and cellular adaptation." (PMID 39697237, 2024). "Cell fractionation, biochemical and mass spectrometry analyses designed to shed light on mechanisms underlying SMURF2’s alterations in cancer cells were also conducted in this study." (PMID 31003445, 2019). "Similar to A‐lamins, Smurf2 also appears to be associated with aging and age‐related diseases, including cancer." (PMID 29405587, 2018). "Other cancer causing candidates were SMURF2, PIK3AP1, RSBN1, TTN and SEMA6D, which were ranked in the top 25% potential drivers in transposon insertional mutagenesis studies in mice." (PMID 29854292, 2018). "Lowly-connected interfacing proteins are no less interesting, as they include the HCV-binding protein SMURF2 and the cancer-mutated gene TPR, both of which have a connectivity of three." (PMID 24564909, 2013). "The latest study from the Zhang group reported that mice deficient in Smurf2 are prone to various types of cancers at old age despite being able to develop normally." (PMID 22429979, 2012). "Smurf2 (Sma and Mad ubiquitination regulatory factor 2), an E3 ligase belonging to the neuronally expressed developmentally downregulated 4 family of proteins, has been implicated in tumorigenesis across various cancer types." (PMID 40978141, 2025). "As shown in this study, low Smurf2 expression was associated with accelerated cell migration and an increase in stem cell-like properties and CTCs, which indicates the aggressive behavior of cancer cells." (PMID 35361871, 2022). "Like SMURF1, SMURF2 is also associated with different types of human cancers." (PMID 33418880, 2021). "Additionally, high levels of Smurf2 expression have been found in association with several types of cancer and were correlated with poor prognosis." (PMID 32733916, 2020). "However, the mechanisms underlying SMURF2 inactivation in human malignancies remain elusive, as SMURF2 is rarely found mutated or deleted in cancers." (PMID 31003445, 2019). "Further studies uncovered that SMURF2 protein stability is dramatically increased in the cytoplasm in comparison to the SMURF2’s nuclear pool, suggesting it as a mechanism underlying the cytoplasmic accumulation of SMURF2 in cancer." (PMID 31003445, 2019). "However, the mechanism underlying these dual roles for Smurf2 in cancer remain poorly understood." (PMID 32733916, 2020). "At the same time, curcumin has been shown to enhance pyroptotic cell death in cancer by stabilizing NLRP3 via inhibition of Smurf2, thereby activating the inflammasome complex." (PMID 40806716, 2025). "SMURF2 plays a crucial functional role in inhibiting cancer cell proliferation and tumorigenesis, achieved by promoting ubiquitination and degradation of several vital cellular proteins." (PMID 38698292, 2025). "Co-expression of DDX3XR326H and SMURF2 resulted in cytoplasmic sequestration of the latter, a phenotype previously observed for SMURF2 in cancer cells." (PMID 39836689, 2025). "Alterations in the SMURF2-HIF1α interaction can affect these processes, offering targets to enhance cancer treatment and potentially bypass resistance to existing therapies." (PMID 39697237, 2024).
cancer (continued). "By reducing HIF1α levels, SMURF2-mediated degradation disrupts key adaptive responses in tumors, such as angiogenesis and metabolic reprogramming, both essential for cancer cell survival in hypoxic conditions." (PMID 39697237, 2024). "Introducing compounds such as Pep7 reduces SMURF2’s cellular levels, affecting cancer cell proliferation and augmenting cancer therapy by increasing the cytotoxicity of existing treatments." (PMID 39697237, 2024). "Leveraging the relationship between HIF1α and the TME through the SMURF2-HIF1α axis offers a multifaceted strategy for cancer treatment, particularly beneficial in tumors resistant to traditional therapies targeting the von Hippel-Lindau-HIF1α pathway." (PMID 39697237, 2024). "SMURF2 targets HIF1α for ubiquitination and subsequent proteasomal degradation, disrupting hypoxic responses that promote cancer cell survival, metabolic reprogramming, angiogenesis, and resistance to therapy." (PMID 39697237, 2024). "Although the SMURF2-HIF1α pathway holds promise for managing cancer cell survival and resistance in the hypoxic TME, its clinical application remains to be developed." (PMID 39697237, 2024). "Recent studies have highlighted the complex interactions between CDK4/6, HIF1α, and SMURF2, particularly in regulating HIF1α stability, which has significant implications for cancer progression." (PMID 39697237, 2024). "While our review reveals the critical role of the SMURF2-HIF1α pathway in cancer progression and therapy resistance, it is crucial to consider the potential side effects and economic implications of new therapies." (PMID 39697237, 2024). "Further research is essential to fully understand the mechanisms of SMURF2 and their implications for cancer treatment." (PMID 39697237, 2024). "This correlation points to the potential utility of SMURF2 as both a prognostic biomarker and a therapeutic target in cancer." (PMID 39697237, 2024). "The role of SMURF2 extends to maintaining genomic integrity, targeting specific proteins for degradation to prevent aneuploidy and genomic instability—key hallmarks of cancer." (PMID 39697237, 2024). "Targeting the SMURF2-HIF1α axis represents a novel strategy to counteract cancer adaptations within TME." (PMID 39697237, 2024). "This interaction suggests that SMURF2 is not only a regulator of HIF1α but also a potential therapeutic target in cancers where hypoxia plays a critical role." (PMID 39697237, 2024). "By reducing GSTP1 levels, SMURF2 disrupts this protective mechanism, sensitizing cancer cells to ferroptotic cell death." (PMID 39697237, 2024). "While promising, the strategic targeting of the SMURF2-HIF1 pathway in cancer therapy confronts formidable hurdles due to the intricate roles and broad biological activities of SMURF2 and HIF1α." (PMID 39697237, 2024). "As described, SMURF2 plays a dual role in maintaining protein homeostasis and genomic integrity, making it a crucial element in cancer cell survival and proliferation under hypoxic conditions typical of solid tumors." (PMID 39697237, 2024). "Specifically, SMURF2’s role as an E3 ubiquitin ligase in regulating HIF1α stability and activity is central to its function in cancer." (PMID 39697237, 2024). "SMURF2’s regulatory activities extend across multiple cancers, including NSCLC, where it influences chemotherapy and radiation resistance, demonstrating its importance across various cancer types and treatment scenarios." (PMID 39697237, 2024). "This expanded understanding of SMURF2’s regulatory capabilities further highlights its therapeutic potential in targeting complex networks within cancer cells." (PMID 39697237, 2024). "Future research should focus on the development of specific SMURF2 modulators to exploit these pathways in cancer therapy." (PMID 39697237, 2024).
cancer (continued). "This intricate interplay between HSP-90, HSP-70, and the SMURF2-HIF1α axis underscores the necessity of carefully modulated therapies that target these pathways, aiming to overcome cancer cells’ adaptive mechanisms to achieve more durable responses." (PMID 39697237, 2024). "Future research should focus on developing specific SMURF2 inhibitors to enhance cancer cell sensitivity to ferroptosis, potentially overcoming resistance to other cell death mechanisms." (PMID 39697237, 2024). "By focusing on the intersection between the SMURF2-HIF1α pathway and protein degradation, new avenues can be unlocked to combat the ever-evolving landscape of therapeutic resistance in cancer." (PMID 39697237, 2024). "Leveraging SMURF2 to selectively degrade GSTP1 provides a promising approach for driving ferroptosis in cancer cells resistant to conventional therapies." (PMID 39697237, 2024). "While HIF1α is a well-established factor in cancer biology, this review article focuses on the intricate interplay between SMURF2 and HIF1α." (PMID 39697237, 2024). "The degradation of GSTP1 by SMURF2 not only diminishes the cell’s ferroptotic defenses but also sensitizes cancer cells to treatments that induce ferroptosis." (PMID 39697237, 2024). "Continued exploration of the SMURF2-HIF1α pathway will remain a pivotal focus in oncology, with the potential to transform cancer therapy and set new standards in patient care." (PMID 39697237, 2024). "By destabilizing HIF1α, SMURF2 disrupts the hypoxic adaptation mechanisms of cancer cells, thereby reducing their survival advantage and possibly enhancing the efficacy of existing treatments." (PMID 39697237, 2024). "SMURF2’s role in modulating HIF1α stability further underscores its potential as a therapeutic target in cancer." (PMID 39697237, 2024). "The functions of HIF1α and SMURF2 across different cancer types highlight their significance as therapeutic targets." (PMID 39697237, 2024). "This SMURF2-mediated degradation mechanism bypasses the traditional VHL (von Hippel-Lindau) pathway, offering an alternative strategy to control HIF1α levels in cancers where VHL is mutated, such as in renal cell carcinoma." (PMID 39697237, 2024). "The critical interplay within the SMURF2-HIF1α axis highlights its potential as a scientific foundation for developing therapeutic strategies aimed at halting cancer progression and improving clinical outcomes." (PMID 39697237, 2024). "Disruptions in the HIF-1α/SMURF2 axis can impair these processes, providing potential targets for improving cancer treatments and overcoming resistance to existing therapies." (PMID 39697237, 2024). "Smurf1 and Smurf2 are considered to act as both promoters and suppressors under different conditions through regulating certain targets involved in cancer progression." (PMID 37537194, 2023). "Collectively, these results are consistent with the notion that RACK1 is a functional effector of SMURF2 in cancer." (PMID 37828084, 2023). "In future work, it will be crucial to screen and identify SMURF2-specific agonists that activate SMURF2 activity in cancer cells to inhibit RACK1-dependent OC progression." (PMID 37828084, 2023). "According to a recent report, Smurf2 inhibits the proliferation of cancer cells by promoting the ubiquitination and degradation of ChREBP." (PMID 35538534, 2022). "Elevated levels of Smurf2 expression have also been detected in other cancers, such as pancreatic, renal, and breast cancers." (PMID 35710591, 2022). "Using in vitro experiments, we demonstrated that the knockdown of Smurf2 expression accelerated cell migration, promoted sphere formation, and increased the expression of EpCAM, a cancer stem cell marker." (PMID 35361871, 2022). "Supporting the EpCAM expression results, Smurf2 knockdown was associated with the increase in the sphere formation rate, indicating that a decrease in Smurf2 expression increased the stem cell-like properties of cancer cells." (PMID 35361871, 2022).
cancer (continued). "Cell invasiveness is an important property in the metastatic cascade of cancer; therefore, the effect of Smurf2 on cell invasiveness was assessed." (PMID 35361871, 2022). "In conclusion, high Smurf2 expression in cancer cells is an independent predictor of better prognosis in patients with primary CRC and corresponding liver metastases." (PMID 35361871, 2022). "In this study, we established for the first time the feasibility of using Smurf2, a protein from the UPS family, as a killing domain in chimeric proteins that successfully causes targeted cancer cell death." (PMID 36612252, 2022). "To assess the effect of Smurf2 on the cancer stem cell-like properties, we performed a sphere formation assay." (PMID 35361871, 2022). "Smurf2 specifically has been shown to have an ambivalent role in cell functions, but has also been shown to have a connection to cancer, as described in the introduction." (PMID 36612252, 2022). "Protein levels of Smurf2 were found to be lower in human lymphoma and breast cancer tissues relative to non-cancer tissues." (PMID 36612252, 2022). "The biological functions of Smurf2 and its related regulatory proteins are crucial for cancer progression and cancer treatment strategies." (PMID 35509688, 2022). "A recent study on the HECT E3 ligase SMURF2 detected the phosphorylation of S384 in cells treated with etoposide, a chemotherapeutic used to treat various cancers." (PMID 35327659, 2022). "Although considerable evidence demonstrating the involvement of Smurf2 in cancer biology has been accumulated, the role of Smurf2 remains controversial." (PMID 35361871, 2022). "In subsequent studies, it would be essential to test the involvement of Smurf2 in HIF-1α regulation in various cancer types especially including both VHL-sufficient and VHL-deficient cancers." (PMID 34611473, 2021). "Conversely, increased expression of SMURF2 correlates with heightened invasion and lymph node metastases and poor prognosis in some cancers." (PMID 33418880, 2021). "On the contrary, Smurf2 can prevent cell migration by targeting other proteins, thus having the opposite effect in cancer progression." (PMID 33114139, 2020). "In contrast, functional Smurf2 inhibits cancer cell proliferation and tumorigenesis via ubiquitination and degradation of several critical cellular proteins, such as Sirtuins, SIRT1, ChREBP, and RNF20." (PMID 32733916, 2020). "A recent study in HepG2 cells showed that TRB3 promoted cancer cell migration and invasion through enhancement of Smurf2 ubiquitylation." (PMID 32733916, 2020). "Neddylation sites and substrates of neddylated Smurf2 in cancer cells need to be further investigated." (PMID 33718111, 2020). "Accumulating evidence indicates that ubiquitylation and degradation of Smurf2 promote the development of some diseases, such as fibrosis and cancer." (PMID 32733916, 2020). "In sum, Smurf1 and Smurf2 are key proteins in the regulation of cancer metastasis, albeit further investigations are required to further elucidate their opposite roles in cell migration and invasion." (PMID 33114139, 2020). "At the transcriptional levels, Smurf2 mediates degradation of transcriptional factors (e.g., KLF5, YY1), which blocks cell proliferation, and decreases susceptibility to various cancers by maintaining genomic stability." (PMID 33718111, 2020). "In fact, the reduction of SMURF2 levels by siRNA or inhibitors leads to a decrease not only in cell survival/proliferation but also in migration and invasive abilities of cancer cells." (PMID 31581360, 2019). "It is, therefore, plausible to assume that in cancer cells, where the abundance of 14-3-3s is increased, 14-3-3s sequester SMURF2 more efficiently, affecting SMURF2 protein turnover and leading to its accumulation in the cytoplasm." (PMID 31003445, 2019).
cancer (continued). "To identify the molecular mechanism of miR‐195 and miR‐497 in cancer, we selected the SMURF2 gene among the components of TGF‐β signaling as putative targets of miR‐195 and miR‐497 using prediction databases." (PMID 31581360, 2019). "We found significant changes in SMURF2 protein localization in cancer versus normal tissues with elevated cytoplasmic and reduced nuclear levels of SMURF2 in cancer tissues." (PMID 31003445, 2019). "TGF‐β1 increases migration and invasion of the cells during metastasis, but the reduction of SMURF2 by siRNA or inhibitors leads to a decrease in the invasion ability of cancer cell." (PMID 31581360, 2019). "Another possibility for elevated levels of SMURF2 in the cytoplasmic compartment of cancer cells is the differential protein stability of cytoplasmic versus nuclear pools of SMURF2." (PMID 31003445, 2019). "Taken together, these findings strongly suggest that Smurf2, similar to A‐lamins, is intrinsically involved in aging and age‐related diseases, including cancer." (PMID 29405587, 2018). "The authors also reported that the loss of Smurf2 destabilizes EGFR, and reduces the clonogenic survival of EGFR-expressing cancer cell strains." (PMID 30116722, 2018). "Despite the heterogenic expression of Smurf2 and A‐lamins, our results pointed to the reciprocal relationship between these proteins also in human cancer tissues." (PMID 29405587, 2018). "We observed that, malignant tumors were 24.88 times more likely to exhibit moderate/intense expression of Smurf2, when non-malignant tumor was the reference (OR =24.88, 95% CI: 7.05–87.79)." (PMID 29534682, 2018). "The effects of Smurf2 depletion on EGFR-negative cancer cells, normal fibroblasts, and on normal epithelial cells were minor." (PMID 30116722, 2018). "We have also observed the reciprocal relationship between decreased levels of A‐lamins and increased levels of Smurf2, and vice versa, in cancer tissues." (PMID 29405587, 2018). "Altogether, these findings motivate the investigation of the therapeutic efficacy of Smurf2 knockdown in treating CNKSR2-addicted cancers more effectively either as an individual therapy or in combination with already existing chemotherapy and/or radiotherapy." (PMID 29534682, 2018). "Our studies have shown that 56 out of 62 malignant tumors (90.32%) showed intense expression of Smurf2 whereas only 6 out of 22 non-malignant tumors (27.27%) showed high Smurf2 positivity (P < 0.001)." (PMID 29534682, 2018). "Collectively, these findings support a potential role for MIR503HG in cancer cell proliferation through the miR-503/Smurf2/TGFBR axis and indicate that MIR503HG is a potential marker in ALK-negative ALCL." (PMID 29758012, 2018). "A few studies have shown that Smurf2 is intrinsically involved in these critical for cancer progression processes." (PMID 30116722, 2018). "It is possible that overexpressed and mislocalized Smurf2 is employed by the carcinogenic machinery to promote oncogenesis, at least in some types of cancer." (PMID 30116722, 2018). "In this regard, it will be even more important to investigate the role of the Smurf2/GSK3β/SCFβ−TrCP/Ras module in animal cancer models and in clinical samples." (PMID 30116722, 2018). "Previous studies have shown that Smurf2 suppresses the TGFBR via ubiquitin-mediated degradation in cancer cells." (PMID 29758012, 2018). "Understanding of these mechanisms is imperative in explaining the dual role of Smurf2 in cancer and its impact on cancer progression and treatment." (PMID 30116722, 2018). "The most surprising and exciting finding on the involvement of Smurfs, in particular of Smurf2, in cancer we, and subsequently another group, obtained using Smurf2-depleted mice (Smurf2−/− mice)." (PMID 30116722, 2018). "Smad7 and Smurf2 have been identified as TGFβ signaling inhibitors that are overexpressed in some types of cancer." (PMID 28431583, 2017).